XIST (X inactive specific transcript)
Diseases named in the same sentence as XIST in open-access papers (continued):
Sharing a sentence is not in itself a finding about the gene and the disease.
thyroid cancer (continued). "In thyroid cancer, the XIST/miR-34a axis could promote cell proliferation and tumor growth by regulating MET-PI3K-AKT signaling." (PMID 32127028, 2020). "XIST may compete with c-Met for miR-34a binding, which promotes thyroid cancer cell proliferation and tumor growth." (PMID 32219093, 2020). "The area under the curve (AUC) was 0.7360 (P < 0.0001), suggesting the potential of XIST expression as a novel biomarker for thyroid cancer and might help with diagnosis and monitor therapeutic efficacy." (PMID 30463570, 2018). "Herein, we also observed an up-regulated expression of XIST in 77 thyroid cancer tissues." (PMID 30463570, 2018). "To investigate whether XIST modulates the cell proliferation and tumor growth of thyroid cancer through interacting with miRNAs, we searched online database Gene Expression Omnibus (GEO) for dysregulated miRNAs." (PMID 30463570, 2018). "Based on online database and online tool prediction results, miR-34a was underexpressed in thyroid cancer and might be a direct target of XIST." (PMID 30463570, 2018). "Targeting lncRNA XIST may also be a promising approach to treating thyroid cancer." (PMID 39458944, 2024). "Artemisinin may respond to the progression of thyroid cancer promoted by high expression of XIST." (PMID 37036874, 2023). "However, whether XIST plays a potential role in thyroid cancer through interacting with miRNA remains unclear." (PMID 30463570, 2018). "In this study, we will verify the mechanism that XIST regulates glycolysis of thyroid cancer cells through HIF-1a, and explore XIST as a biomarker of thyroid cancer progression and corresponding intervention measures." (PMID 37036874, 2023). "XIST and MET protein compete for the combination of miR-34a, which in turn leads to the progression of thyroid cancer." (PMID 36035993, 2022). "A few months later, another research group reported that XIST functioned as a miR-34a sponge, competing with MET to regulate cell growth in thyroid cancer." (PMID 34930117, 2021). "XIST serves as a ceRNA for miR-34a through sponging miR-34a, competing with MET for miR-34a binding, and finally modulating thyroid cancer cell proliferation and tumor growth." (PMID 30463570, 2018). "Contrary to miR-34a, MET mRNA expression and protein level were significantly increased in thyroid cancer tissue samples; moreover, MET expression was positively correlated with XIST, whereas negatively correlated with miR-34a expression." (PMID 30463570, 2018). "Furthermore, XIST facilitates cell invasion and migration by directly modulating the miR-101-3p/CLDN1 axis and providing new insight into thyroid cancer treatment." (PMID 34930117, 2021). "Briefly, the expression of XIST in thyroid cancer and adjacent non-tumor tissues was first examined." (PMID 30463570, 2018). "Herein, we searched TCGA-THCA for dysregulated lncRNAs, among which XIST is considered to be significantly increased in thyroid cancer compared to normal non-tumor tissues." (PMID 30463570, 2018). "In a total of 77 paired thyroid cancer and non-tumor tissue samples, we detected the expression of XIST using real-time PCR assays." (PMID 30463570, 2018). "In thyroid cancer, XIST may serve a ceRNA for miR-34a to compete with MET for miR-34a binding, thus affecting thyroid cancer cell proliferation and tumor growth." (PMID 30463570, 2018). "XIST expression was significantly increased in thyroid cancer tissue samples, compared to adjacent non-tumor tissue samples, based on the data from TCGA-THCA." (PMID 30463570, 2018).
cervical cancer (19 papers, 2017 to 2025). A primary or metastatic malignant neoplasm involving the cervix. "Studies have shown that lncRNA XIST promotes cervical cancer progression by upregulating FUS via competitively binding to miR-200a." (PMID 36879084, 2023). "Overexpression of ORC1 mediated by the lncRNA XIST/miR‐140‐5p axis promotes the progression of cervical cancer." (PMID 36205357, 2023). "For example, XIST was reported to facilitate cervical cancer progression through up-regulating Fus via competitively binding with miR-200a." (PMID 35101035, 2022). "For instance, XIST upregulates Fus (fused in sarcoma) via competitive binding with miR-200a, which in turn acts as a ceRNA in the development of cervical cancer." (PMID 36035993, 2022). "A previous study confirmed that in cervical cancer, XIST promoted cell proliferation and suppressed cell apoptosis via miR-140-5p." (PMID 32127028, 2020). "Our study indicated the effects of XIST/miR-140-5p/ORC1 axis on the progression of cervical cancer which will shed new light on epigenetic diagnostics and therapeutics in cervical cancer." (PMID 30858762, 2019). "Although our study showed the impacts of XIST on cervical cancer progression through miR-140-5p/ORC1 axis, there were still some deficiencies remained to improve." (PMID 30858762, 2019). "Although XIST is concerned with the survival rate in cervical cancer patients, the exact modulating mechanism and the impacts of XIST on cancer cells are still worth to be further studied." (PMID 30858762, 2019). "All of these results above proved that XIST played a significant role in the cervical cancer metastatic." (PMID 30858762, 2019). "Our data indicated that XIST expression in cervical cancer tissues was statistically correlated with larger tumor size, advanced FIGO stage, well tumor differentiation and lymphatic metastasis." (PMID 30858762, 2019). "In conclusion, our study proved that the XIST contributed to progression of cervical cancer cells by inhibiting miR-140-5p." (PMID 30858762, 2019). "We found an evident increase of XIST expression in cervical cancer, and the downregulation of XIST inhibited cell proliferation and cell cycle as well as induced cell apoptosis in the present study." (PMID 30858762, 2019). "The results turned out that XIST expression level in cervical cancer tissues was dramatically higher than that in adjacent tissues." (PMID 30858762, 2019). "In our study, we conducted immunohistochemistry staining to determine the expression of Ki-67, E-cadherin and vimentin, the results showed that Ki-67 and vimentin was decreased in cervical cancer tissues while E-cadherin was increased when we knockdown XIST." (PMID 30858762, 2019). "Si-XIST vector transfected Hela cells were inoculated into the mice to confirm the XIST effects on cervical cancer tumorigenesis." (PMID 30858762, 2019). "Recently, XIST was demonstrated to accelerate cervical cancer progression in vitro, including cell proliferation, apoptosis, invasion." (PMID 30858762, 2019). "In addition, MALAT1, PVT1, H19, and XIST can promote cancer cell proliferation, invasion, and migration and play a role in the progression of cervical cancer." (PMID 35262965, 2022). "XIST can accelerate cervical cancer via inducing Fus by sponging miR-200a." (PMID 34258298, 2021). "The hnRNP P2 (FUS/TLS) is highly expressed in cervical cancer as well as in SiHa and HeLa cells, dependently from the activation of XIST lncRNA/miR-200a axis, and induces the epithelial mesenchymal transition phenotype and proliferation while inhibiting apoptosis in cervical cancer cells." (PMID 32596243, 2020). "As FUS is a member of the TET protein family, this protein was found to be inversely regulated by miR-141 in human neuroblastoma and can be activated by lncRNA XIST, which also served as a ceRNA in cervical cancer progression while competitively binding with miR-200a." (PMID 32117463, 2020).
cervical cancer (continued). "Additionally, when compared with human cervical epithelial cell line HcerEpic, XIST expression was ubiquitously increased in four cervical cancer cell lines (CaSki, Hela, C33A, SiHa)." (PMID 30858762, 2019). "Firstly, we divided 30 patients into two groups in accordance with the average XIST expression level (high XIST group: XIST expression level > average; low XIST group: XIST expression level ≤ average) to investigate the significance of XIST in cervical cancer." (PMID 30858762, 2019). "Besides the flow cytometry results demonstrated that cell cycle was blocked in G0 phase by si-XIST, whereas the apoptosis cells were increased in cervical cancer cells transfected with si-XIST compared to NC group." (PMID 30858762, 2019). "And the results of cell apoptosis analysis were consistent with the previous experiments, si-ORC1 could significantly promote the apoptosis rate of cervical cancer cells, and miR-140-5p inhibitor and XIST could offset the role of si-ORC1." (PMID 30858762, 2019). "Likewise, we found significant overexpression of XIST in cervical cancer tissues as well as cell lines (Hela and C33A), accelerated the cancer cell proliferation and suppressed cell apoptosis." (PMID 30858762, 2019). "As we also validated that knock-down of XIST could suppress tumor growth in vivo which further confirmed the effects of XIST on cervical cancer progression." (PMID 30858762, 2019). "In a nutshell, our findings documented that XIST may play a vital role in cervical cancer." (PMID 30858762, 2019). "Besides, we found the targeting relationship between miR-140-5p and ORC1, and related cell experiments further proved that XIST could regulate ORC1 by targeting miR-140-5p to affect the progress of cervical cancer." (PMID 30858762, 2019). "In addition, there may exist other miRNAs and possible mechanisms of XIST in cervical cancer, like miR-200a." (PMID 30858762, 2019). "With regard to miR-889-3p function, lncRNA XIST modulates the miR-889-3p/SIX1 axis and participates in cervical cancer progression." (PMID 34858987, 2021). "Up-regulated lncRNA XIST facilitated cell cycle and EMT process in cervical cancer via reducing miR-140-5p." (PMID 32669970, 2020). "Then, the expression of XIST, miR-140-5p, and ORC1 were detected using qRT-PCR and western blot in both tissues and cervical cancer cell lines (Hela and C33A) to verify the bioinformatics analyses results." (PMID 30858762, 2019). "MiR-140-5p was down-regulated but XIST and ORC1 were up-regulated in cervical cancer tissues and cell lines." (PMID 30858762, 2019). "Thus, we wanted to know more about the XIST’s effects on cervical cancer cells remains unclear." (PMID 30858762, 2019). "Moreover, we carried a further exploration of the mechanism of XIST/miR-140-5p axis including the targeting gene ORC1, and provided a new therapeutic method for cervical cancer." (PMID 30858762, 2019). "It was also proved that the XIST expression was correlated with the survival rate on the whole in patients who have cervical cancer, while the regulation process in the cancer cells have not been discussed yet." (PMID 30858762, 2019). "Besides, XLOC_010588, XIST, LET, MEG3 were correlated to poor prognosis with the low expressions of lncRNAs in cervical cancer." (PMID 28977961, 2017).
osteosarcoma (19 papers, 2017 to 2025). A usually aggressive malignant bone-forming mesenchymal neoplasm, predominantly affecting adolescents and young adults. "XIST was significantly upregulated in osteosarcoma tissues and cell lines, and increased XIST expression was associated with the poor overall survival of patients." (PMID 33653335, 2021). "For instance, lncRNA XIST in MSC-EVs can promote osteosarcoma growth and metastasis through the miR-655/ACLY signaling." (PMID 38697996, 2024). "The presence of lncRNA XIST in MSC-EVs promotes osteosarcoma growth and metastasis through the miR-655/ACLY signaling pathway." (PMID 38697996, 2024). "This indicated that BMSCs derived exosomal XIST can promote osteosarcoma progression by binding miR-655." (PMID 36309693, 2022). "On the basis of down-regulation of XIST, after the expression of miR-655 in osteosarcoma cells was inhibited, the cell proliferation, migration and invasion in vitro, tumor growth and metastasis in vivo were significantly restored." (PMID 36309693, 2022). "Based on previous studies, it was found that BMSCs derived exosomes XIST were mainly localized in the cytoplasm after entering osteosarcoma cells." (PMID 36309693, 2022). "We found for the first time that BMSCs derived exosomes can transmit XIST to promote osteosarcoma progression." (PMID 36309693, 2022). "We intended to explore the mechanism of BMSCs derived exosomal XIST promoting osteosarcoma progression through miRNA." (PMID 36309693, 2022). "In order to further clarify the mechanism of promoting osteosarcoma progression by BMSCs derived exosomal XIST combined with miR-655, we first analyzed the target gene of miR-655 through Starbase 3.0." (PMID 36309693, 2022). "Studies have shown that XIST can regulate the progression of osteosarcoma, and BMSCs derived exosomes can increase the level of XIST in osteosarcoma cells." (PMID 36309693, 2022). "In order to further clarify the effect of BMSCs derived exosomal XIST combined with miR-655 on osteosarcoma, we established an osteosarcoma in situ model by injecting 143B/LUC cells into the tibial bone marrow cavity of BALB/c nude mice." (PMID 36309693, 2022). "It was found that BMSCs derived exosomes promoted the proliferation, migration and invasion of osteosarcoma cells, and the down-regulation of XIST inhibited this effect." (PMID 36309693, 2022). "For example, in osteosarcoma, the expression of XIST is up-regulated, which is closely related to tumor size, clinical stage and distant metastasis." (PMID 36309693, 2022). "XIST is another potential biomarker of osteosarcoma which has been reported to modulate osteosarcoma proliferation and invasion through miR-320b/RAP2B, miR-193a-3p/RSF1, miR-21-5p/PDCD4, and miR-195-5p/YAP axis." (PMID 33639865, 2021). "Recently, increased XIST expression in osteosarcoma cells has suggested a new role of this ncRNA in cell proliferation." (PMID 31068966, 2019). "This study investigated the effects and mechanisms of targeting XIST on osteosarcoma (OS) cells in vitro and in vivo." (PMID 31189404, 2019). "Very recently, some authors revealed that the inhibition of XIST fine-tuned cell proliferation and the apoptosis rate by regulating the expression levels of p-p65 and p-IκBα NF-KB in human osteosarcoma cells and in rheumatoid arthritis fibroblast-like synoviocytes." (PMID 40136478, 2025). "Meanwhile, animal level results confirmed that BMSCs derived exosomal XIST could promote osteosarcoma growth and lung metastasis by combining with miR-655." (PMID 36309693, 2022). "Further functional analysis showed that BMSCs derived exosomes increased the osteosarcoma cell viability, DNA replication, migration and invasion, while down-regulating the level of XIST could significantly inhibit those effects." (PMID 36309693, 2022). "It was found that BMSCs derived exosomes could promote the expression of ACLY in osteosarcoma cells, inhibition of XIST expression reduces ACLY level." (PMID 36309693, 2022).
osteosarcoma (continued). "The results showed that BMSCs derived exosomal XIST could bind miR-655 based on ceRNA mechanism after it enter into osteosarcoma cells." (PMID 36309693, 2022). "This indicated that osteosarcoma cells could uptake BMSCs derived exosomes, resulting in an increase in the level of XIST in the cells." (PMID 36309693, 2022). "Finally, we analyzed the effect of BMSCs derived exosomal XIST on the biological function of osteosarcoma by enhancing ACLY expression in combination with miR-655." (PMID 36309693, 2022). "So the next question was whether the BMSCs derived exosomal XIST affect the biological function of osteosarcoma cells by binding miR-655." (PMID 36309693, 2022). "We found that XIST was mainly localized in the cytoplasm of osteosarcoma cells." (PMID 36309693, 2022). "In osteosarcoma, most studies have shown that XIST plays a role in promoting cancer." (PMID 36309693, 2022). "The results indicated that BMSCs derived exosomes could enhance osteosarcoma cell proliferation, migration and invasion through XIST." (PMID 36309693, 2022). "miR-655 mediated the role of BMSCs derived exosomal XIST in promoting the progression of osteosarcoma and down-regulation of miR-655 could reverse the effects of inhibiting XIST on the proliferation, migration and invasion of osteosarcoma cells." (PMID 36309693, 2022). "A negative association between XIST expression and OS of osteosarcoma patients was noticed (HR = 1.79, 95%CI: 1.40–2.30, P < 0.001) based on the analysis of four researches containing 299 patients." (PMID 33639865, 2021). "Knockdown of XIST can inhibit proliferation of osteosarcoma cells." (PMID 33228517, 2020). "XIST is a markedly elevated lncRNA in osteosarcoma tissues and cells." (PMID 32779318, 2020). "However, whether BMSCs derived exosomes transmit XIST to regulate the growth and metastasis of osteosarcoma and the related mechanism are still unclear." (PMID 36309693, 2022). "In this study, BMSCs derived exosomes were used to treat human osteosarcoma cells MG63 and 143B, and the level of XIST in BMSCs was intervened by siRNA." (PMID 36309693, 2022). "Osteosarcoma cell lines MG63 and 143B were treated with BMSCs derived exosomes of different concentrations, and the level of XIST in cells was significantly increased." (PMID 36309693, 2022). "In addition, inhibition of miR-655 could effectively antagonize the effect of BMSCs derived exosomes XIST on the level of XIST in osteosarcoma cells, suggesting that XIST and miR-655 in osteosarcoma cells could bind and regulate the level of each other, that is, there was a ceRNA mechanism." (PMID 36309693, 2022). "Concretely, higher methylation level of XIST indicated shorter overall survival rates of patients with BRCA, UCEC and osteosarcoma, but predicted better prognosis of KIRC." (PMID 36212008, 2022). "Their high expression predicted poor prognosis of osteosarcoma (MALAT1 (HR = 2.15, 95%CI: 1.67–2.76, P < 0.001), TUG1 ((HR = 2.41, 95%CI: 1.42–4.07, P = 0.001), XIST (HR = 1.79, 95%CI: 1.40–2.30, P < 0.001), NEAT1 (HR = 1.96, 95%CI: 1.05–3.68, P = 0.035))." (PMID 33639865, 2021). "Further, analysis toward osteosarcoma clinicopathologic features demonstrated that overexpression of TUG1 and XIST indicated poor clinical parameters of patients." (PMID 33639865, 2021). "Fluorescence in situ hybridization (FISH) experiment also confirmed that the treatment with BMSCs derived exosomes on osteosarcoma cell lines MG63 and 143B could increase the level of XIST in these cells, and XIST was mainly localized in the cytoplasm." (PMID 36309693, 2022). "We found that BMSCs derived exosomal XIST combined with miR-655 could increase the expression level of ACLY and promote the proliferation, migration and invasion of osteosarcoma cells." (PMID 36309693, 2022). "There results showed that BMSCs derived exosomal XIST could increase the ACLY level by binding miR-655, thereby promoting the proliferation of osteosarcoma cells." (PMID 36309693, 2022).